GBF1 (golgi brefeldin A resistant guanine nucleotide exchange factor 1)
Description:
Guanine-nucleotide exchange factor (GEF) for members of the Arf family of small GTPases involved in trafficking in the early secretory pathway; its GEF activity initiates the coating of nascent vesicles via the localized generation of activated ARFs through replacement of GDP with GTP. Recruitment to cis-Golgi membranes requires membrane association of Arf-GDP and can be regulated by ARF1, ARF3, ARF4 and ARF5. Involved in the recruitment of the COPI coat complex to the endoplasmic reticulum exit sites (ERES), and the endoplasmic reticulum-Golgi intermediate (ERGIC) and cis-Golgi compartments which implicates ARF1 activation. Involved in COPI vesicle-dependent retrograde transport from the ERGIC and cis-Golgi compartments to the endoplasmic reticulum (ER). Involved in the trans-Golgi network recruitment of GGA1, GGA2, GGA3, BIG1, BIG2, and the AP-1 adaptor protein complex related to chlathrin-dependent transport; the function requires its GEF activity (probably at least in part on ARF4 and ARF5). Has GEF activity towards ARF1. Has in vitro GEF activity towards ARF5 (By similarity). Involved in the processing of PSAP. Required for the assembly of the Golgi apparatus. The AMPK-phosphorylated form is involved in Golgi disassembly during mitotis and under stress conditions. May be involved in the COPI vesicle-dependent recruitment of PNPLA2 to lipid droplets; however, this function is under debate. In neutrophils, involved in G protein-coupled receptor (GPCR)-mediated chemotaxis und superoxide production. Proposed to be recruited by phosphatidylinositol-phosphates generated upon GPCR stimulation to the leading edge where it recruits and activates ARF1, and is involved in recruitment of GIT2 and the NADPH oxidase complex. Plays a role in maintaining mitochondrial morphology.
Synonyms: KIAA0248; ARF1GEF; CMT2GG; CMTDI2; CMTDIA
Tractability: Antibody: UniProt places it where antibodies can reach, with high confidence. PROTAC: ubiquitination databases record sites on it; its protein half-life has been measured.
Gene: Protein-coding gene on chromosome 10 (102,245,371 to 102,382,899, forward strand). Ensembl gene ENSG00000107862.
Subcellular location: Golgi apparatus, cis-Golgi network; Endoplasmic reticulum-Golgi intermediate compartment; Golgi apparatus, trans-Golgi network; Golgi apparatus; Cytoplasm; Lipid droplet; Membrane
Subcellular location (Human Protein Atlas): Golgi apparatus
Pathways (Reactome):
Vesicle-mediated transport: COPI-dependent Golgi-to-ER retrograde traffic; COPI-mediated anterograde transport; trans-Golgi Network Vesicle Budding
Disease: Assembly and Release of Dengue Virus Virions; Dengue Virus-Host Interactions
Organelle biogenesis and maintenance: VxPx cargo-targeting to cilium
Gene Ontology:
Molecular function: phosphatidylinositol-3,4,5-trisphosphate binding; phosphatidylinositol-3,5-bisphosphate binding; protein binding; guanyl-nucleotide exchange factor activity
Biological process: cell activation involved in immune response; COPI coating of Golgi vesicle; Golgi to endosome transport; neutrophil chemotaxis; retrograde transport, endosome to Golgi; retrograde vesicle-mediated transport, Golgi to endoplasmic reticulum; cilium assembly; endoplasmic reticulum to Golgi vesicle-mediated transport; Golgi organization; post-Golgi vesicle-mediated transport; regulation of ARF protein signal transduction
Cellular component: cell leading edge; cis-Golgi network; cytoplasm; endoplasmic reticulum-Golgi intermediate compartment; Golgi apparatus; lipid droplet; membrane; trans-Golgi network; cytosol; endoplasmic reticulum lumen; Golgi cis cisterna; Golgi membrane; Golgi stack; peroxisome
Genetic constraint (gnomAD): Loss-of-function variants: 76 observed, 143.35 expected, observed/expected ratio (o/e) 0.53, 90% interval 0.44 to 0.64. The upper end of that interval is the gene's LOEUF score, 0.64, which puts it in group 2 of 6, group 1 being the genes least tolerant of losing a copy. Missense variants: 1,418 observed, 1,916.6 expected, observed/expected ratio (o/e) 0.74, 90% interval 0.71 to 0.77. Synonymous variants: 664 observed, 741.62 expected, observed/expected ratio (o/e) 0.9, 90% interval 0.84 to 0.95.
Homologues: Orthologues: chimpanzee GBF1 (99% identical), macaque GBF1 (97% identical), pig GBF1 (97% identical), dog GBF1 (96% identical), rabbit GBF1 (96% identical), rat Gbf1 (94% identical), mouse Gbf1 (94% identical), guinea pig GBF1 (93% identical), tropical clawed frog gbf1 (79% identical), zebrafish gbf1 (75% identical), Drosophila melanogaster garz (44% identical), Caenorhabditis elegans gbf-1 (40% identical), and 4 more. Paralogues in human: ARFGEF2 (19% identical), ARFGEF1 (19% identical), IQSEC1 (11% identical), IQSEC2 (10% identical), MON2 (10% identical), IQSEC3 (10% identical), CYTH1 (8% identical), CYTH2 (8% identical), CYTH3 (8% identical), CYTH4 (8% identical), PSD3 (8% identical), PSD4 (7% identical), and 3 more.
Diseases named in the same sentence as GBF1 in open-access papers:
GBF1 is named in the same sentence as 35 diseases in open-access papers, as found by Europe PMC text mining. Sharing a sentence is not in itself a finding about the gene and the disease. The quoted sentences say what the papers report.
viral infections (5 papers, 2008 to 2022). "Given that a previous report showed that GBF1, which is an essential factor for viral replication, transiently overlaps dsRNA early in infection, cleavage of p115 may ensure that the association of GBF1 with dsRNA is transient during virus infection." (PMID 29437971, 2018). "The relevance of GBF1 for the replication of several RNA viruses identifies this factor as a potential candidate for antiviral therapies to control a broad-spectrum of viral infections." (PMID 32599855, 2020). "GBF1, a guanine nucleotide exchange factor for the small cellular GTPases, Arf, is responsible for the sensitivity of virus infection to BFA, and is required for virus replication." (PMID 19023417, 2008). "During viral infections, GBF1 is generally assumed to function as an ArfGEF by activating Arf1, which in turn would recruit the COP-I coatomer, molecular machinery involved in intracellular transport, which has also been shown to be required for the replication of several positive RNA viruses." (PMID 25517881, 2014). "The mechanism of action of GBF1 in viral infections is not yet fully understood." (PMID 25517881, 2014). "The role of GBF1 has been found, principally, to depend on its ability to activate distinct Arf proteins, to regulate different transport pathways that permit the communication between the viral replication organelles and cellular organelles (ER and LDs) involved in virus infection." (PMID 32599855, 2020). "Total GBF1 proteins were increased by AG1478 treatment irrespective of viral infection, which was consistent with IP data and suggested that AG1478 may affect GBF1 protein production." (PMID 35628375, 2022). "However, given the essential role of GBF1 in the secretory pathway, and in other so far ill-characterized functions of the cell, the development of safe and effective antiviral therapies that could help to deal with viral infections, without harming the host cells, represents a challenging mission." (PMID 32599855, 2020).
poliovirus infection (3 papers, 2008 to 2022). An disease or disorder caused by infection with Enterovirus C. "Both GBF1 and p115 become dispersed within the cytoplasm during poliovirus infection, indicating that the Golgi apparatus is fragmented in infected cells." (PMID 29437971, 2018). "During poliovirus infection, GBF1 transiently colocalizes with double-stranded RNA (dsRNA) and 3A protein, which are markers of replication sites (60, –, 62)." (PMID 29437971, 2018). "Both p115 and GBF1, which have been previously characterized during poliovirus infection, are substrates of poliovirus 3Cpro during infection." (PMID 29437971, 2018). "We demonstrate that GBF1 can rescue poliovirus infection from inhibition by BFA, and that reduced interaction between GBF1 and viral protein 3A increases the sensitivity of poliovirus infection to BFA." (PMID 19023417, 2008). "Given that p115 interacts with GBF1, we asked whether cleavage of p115 is a prerequisite for GBF1 interaction with dsRNA during poliovirus infection." (PMID 29437971, 2018). "Recruitment of GBF1 to membranes induced by poliovirus protein 3A leads to a productive cascade of Arf activation and COPI coatomer recruitment, consistent with our previous report that increased levels of Arf-GTP steadily accumulate on membranes with time during poliovirus infection of HeLa cells." (PMID 19023417, 2008).
leukemia (2 papers, 2019 to 2023). A malignant (clonal) hematologic disorder, involving hematopoietic stem cells and characterized by the presence of primitive or atypical myeloid or lymphoid cells in the bone marrow and the blood. "Western blot was performed on ten Golgi proteins (GBF1, GM130, Golgin97, TGN38, GRASP65, GRASP55, BLZF1, STX3, STX6, and GOLPH3) in small-cell lung cancer (SCLC), leukemia, colon cancer, and GIST cell lines expressing WT-KIT or MT-KIT." (PMID 37704840, 2023).
sarcopenia (2 papers, 2023 to 2024). Progressive decline in muscle mass due to aging which results in decreased functional capacity of muscles. "It has previously been shown that two SNPs (MLN rs12055409 and GBF1 rs2273555) associated with higher levels of muscle mass and strength in elite Russian weightlifters protect against sarcopenia." (PMID 39056794, 2024).
Adult onset (1 paper, 2024). Onset of disease manifestations in adulthood, defined here as at the age of 16 years or later. "Our cases describe two siblings diagnosed with possible CMT2GG or AD-CMT2-Ax-GBF1, a newly recognized form of adult-onset peripheral axonal neuropathy associated with mutations in the GBF1 gene, also pointing out a suitable intra-familial clinical variability." (PMID 39766823, 2024).
Anxiety (1 paper, 2023). Intense feelings of nervousness, tension, or panic often arise in response to interpersonal stresses. "Of the 11 gene scores in the anxiety symptom group, we replicated six genes, including CNNM2, EXD3, GBF1, NT5C2, NOLC1 and TRIM." (PMID 37322117, 2023).
Bardet-Biedl syndrome (1 paper, 2024). A ciliopathy with multisystem involvement. "Moreover, the genetic link to GBF1 is more complex since other disease associations for variants within the GBF1 gene comprise the Bardet–Biedl Syndrome, Type 5, and cataracts." (PMID 39766823, 2024).
heart failure (1 paper, 2023). Inability of the heart to pump blood at an adequate rate to meet tissue metabolic requirements. "GBF1 activity is controlled by AMPK, and AMPK, in turn, is activated by a wide range of environmental cues, many of which are closely linked to the pathology of heart failure." (PMID 36901985, 2023).
hepatoma (1 paper, 2012). "For example, a specific pro-survival activity of GBF1, but not BIG1 or BIG2, was observed in human hepatoma cells." (PMID 22485163, 2012).
influenza (1 paper, 2022). An acute viral infection of the respiratory tract, occurring in isolated cases, in epidemics, or in pandemics; it is caused by serologically different strains of viruses (influenzaviruses) designated A, B, and C, has a 3-day incubation period, and usually lasts for 3 to 10 days. "Second, influenza appeared to hijack a significant portion of GBF1 for its own protein transport in the cytoplasm." (PMID 35628375, 2022). "Because targeting host factors, instead of the viral component, imposes a higher barrier for developing resistance, GBF1 modulation may be an effective approach to treat influenza infection." (PMID 35628375, 2022). "In this study, we are the first to link the anti-influenza activity of AG1478 with GBF1, another non-EGFR target." (PMID 35628375, 2022).
Insulin resistance (1 paper, 2017). Increased resistance towards insulin, that is, diminished effectiveness of insulin in reducing blood glucose levels. "Gene GBF1, which was associated with the 46 traits (p-value ≤ 6.30 × 10−28), HOMA-B (p-value ≤ 2.91 × 10−17), has been reported to be involved in insulin resistance and type 2 diabetes." (PMID 29040274, 2017).
melanoma (1 paper, 2023). A malignant, usually aggressive tumor composed of atypical, neoplastic melanocytes. "The results revealed that the CSTB, GBF1, TYR, RAC1, SLC2A1 and NOTCH3-coding proteins were significantly enriched in melanoma samples, while CEBPB-coding protein had low expression in melanoma samples." (PMID 37217516, 2023). "However, the roles of CSTB, GBF1, PML and ICAM1 in melanoma development were still unclear, which deserved to further exploration." (PMID 37217516, 2023).
neuroblastoma (1 paper, 2020). Neuroblastoma (NB) is the most common solid, extracranial childhood tumor. "Additionally, the rs10748818 failed to affect GBF1 promoter transcriptional activity in human T lymphocyte cells and human neuroblastoma cells." (PMID 32652860, 2020).
ovarian carcinoma (1 paper, 2022). A malignant neoplasm originating from the surface ovarian epithelium. "We noted that the mRNA of UBA2, GLO1, TUFT1, HPD, and GBF1 were upregulated in the ovarian cancer samples in comparison to the control samples." (PMID 35992817, 2022).
penile carcinoma (1 paper, 2021).
polio (1 paper, 2008). "Inhibition of polio replication by BFA is specific for the particular host cell, and this specificity is determined by the sequence of the catalytic Sec7 domain of GBF1 in the cell." (PMID 19023417, 2008). "Treatment of cells with zVAD-fmk did not change the reduction of polio replication in cells with knocked down GBF1 expression (not shown)." (PMID 19023417, 2008). "The results of this experiment show that in the presence of BFA, when GBF1-dependent Arf activation could not occur, it is possible to form polio-induced membranous structures morphologically indistinguishable from those developed in the absence of the inhibitor." (PMID 19023417, 2008). "However, expression levels of control proteins from plasmids introduced at the same time as the polio replicon were identical in control cells and cells treated with GBF1 siRNA (not shown), confirming the specificity of inhibition of polio replication by GBF1 knock-down." (PMID 19023417, 2008).
Zika virus infection (1 paper, 2018). "Several studies have identified GBF1 as an important cellular factor for Zika virus infection, as inhibiting GBF1 enzymatic activity by small molecule inhibitors BFA or GCA is detrimental for replication of diverse flaviviruses, including Zika virus." (PMID 30326556, 2018).
infection (24 papers, 2008 to 2025). The state of being infected such as from the introduction of a foreign agent such as serum, vaccine, antigenic substance or organism. "During the infection of macrophages by Yersinia pestis, Rab1b recruitment to the Yersinia-containing vacuole directly inhibits phagosome maturation; active Rab1b stabilizes Arf1 on Golgi membranes, and Rab1b is required for GBF1 membrane association." (PMID 38169281, 2024). "Whether endogenous GBF1 associates with stress granules upon infection, or this phenotype is specific to the truncated APEX2-GARG-1060 construct requires further investigation." (PMID 36306280, 2022). "Infection by EV causes extensive cellular reorganization, including a protein 3A-mediated generation of replication organelles and the recruitment of cellular proteins such as GBF1, ACBD3, and PI4KB, all supporting viral RNA synthesis and virion assembly." (PMID 35458499, 2022). "Upon infection, the viral protein 3A recruits GBF1 and indirectly Arf1 to replication organelles (i.e., virus-induced vesicles plus associated replication complexes) through a direct interaction with GBF1." (PMID 26266417, 2015). "Thus, it has been proposed that although GBF1 is essential for EV replication, the increment of Arf activation detected during infection of some members of EV genus might be a side effect produced by the increased association of GBF1 with membranes." (PMID 32599855, 2020). "Collectively, these findings indicate that, when GCA is applied at 24 hours post-infection, the catalytic activity of GBF1 is dispensable for DENV genome replication but is required for efficient virus secretion and NS1 secretion." (PMID 40838750, 2025). "Specifically, we functionally inhibited GBF1 using GCA at a later stage of infection and found that GCA reduces infectious DENV production in a dose-dependent manner." (PMID 40838750, 2025). "To interrogate the functional role of these host proteins during the P. berghei liver stage infection, we used two pooled siRNAs to knockdown mRNA expression of Arf1, Arf4, and GBF1 in HuH7 cells infected with luciferase-expressing P. berghei (Pb-Luc)." (PMID 38349168, 2024). "GBF1 was internalized by the T. gondii PV starting early in infection (4 hpi) with nearly 100% of T. gondii vacuoles containing at least one punctum by the end of the lytic cycle (48 hpi)." (PMID 38349168, 2024). "This is significant because the GBF1 system appears to be intact after inhibition and the future dosing can be carefully formulated to target certain windows of the infection while minimizing unwanted side effects." (PMID 35628375, 2022). "Here, we demonstrated the function of different GBF1 truncation mutants in CSFV infection and found that CSFV utilized ARF1 in a GBF1 Sec7 domain-dependent manner for infection." (PMID 35044210, 2022). "In agreement with the importance of GBF1 early in infection, it was found that the inhibitory effect of BFA on the replication SINV is lost when this drug is added at late times post infection." (PMID 32599855, 2020). "We compared the changes to Arf1, GBF1, and PI4KB localization caused by 3CD to corresponding changes caused by infection." (PMID 29782554, 2018). "At 4, 6, and 8 hours after infection, the localization coefficient between GBF1 and 3A are less than 0.35." (PMID 28303920, 2017). "BFA inhibits HCV replication when added at the time of or shortly after infection but is less effective at inhibiting replication after infection has been established, suggesting that GBF1 and ARF1 act early in the viral lifecycle." (PMID 22022594, 2011). "We observed that GBF1 and Arf1 have little overlap at the inclusion membrane during infection even though they extensively colocalize at the Golgi surrounding the inclusion." (PMID 21909260, 2011).